CCKAR (cholecystokinin A receptor)
Diseases named in the same sentence as CCKAR in open-access papers (continued):
Sharing a sentence is not in itself a finding about the gene and the disease.
Auditory hallucination (3 papers, 2013 to 2025). Perception of sounds without auditory stimulus. "Moreover, although CCKAR (779 T > C) or CCKBR (1550 G > A) gene polymorphisms alone were not related with visual hallucinations in PD patients in this study, the co-presence of a CCK −45 locus T allele and a CCKAR C allele was significantly associated with a greater risk of visual hallucinations." (PMID 35741861, 2022).
colon cancer (3 papers, 2018 to 2026). "It suggests that targeting CCKAR may represent a potential therapeutic strategy for colon cancer treatment." (PMID 41930160, 2026).
biliary tract cancer (2 papers, 2022 to 2024). "As a hormone modulating gallbladder motility, CCKAR expression or genetic variation is reported to influence hepatocellular carcinoma and biliary tract cancers." (PMID 36733361, 2022).
pancreatic adenocarcinoma (2 papers, 2014 to 2020). "Due to selective expression, CCKAR may serve as potential biomarker for pancreatic adenocarcinoma." (PMID 25025063, 2014).
acral melanoma (1 paper, 2022). "We found that CCKAR was positively stained in the cytoplasm of tumor cells in all superficial spreading melanoma and acral melanoma cases, as represented by two cases of each type." (PMID 36262666, 2022).
alcohol dependence (1 paper, 2023). Physical and psychological dependence on alcohol. "Taken together, our results showed that AD patients’ gut microbiota could induce the disturbances of CCK receptors (especially CCKAR) in rats, which may be one of the molecular mechanisms involved in the development of alcohol dependence." (PMID 37962470, 2023).
anxiety disorder (1 paper, 2025). A category of psychiatric disorders which are characterized by anxious feelings or fear often accompanied by physical symptoms associated with anxiety. "The mechanisms revealed in this study advance our understanding of the emotional regulatory role of CCKAR in the brain, identifying CCKAR in mPOAGad2 neurons as a potential biomarker and therapeutic target for managing anxiety disorders associated with aggression." (PMID 40933818, 2025).
asthma (1 paper, 2023). "Potent bronchodilators are commonly delivered via nebulization, suggesting that CCKAR antagonists may be developed in similar formulation to effectively abrogate asthma symptoms while avoiding undesirable systemic effects." (PMID 36599824, 2023). "However, as our dose regimen is considered acute treatment, it is also unlikely that the action of CCKAR antagonists in reducing AHR in our mouse models was through inhibition of proliferation of asthma-relevant cells such as bronchial epithelial cells." (PMID 36599824, 2023). "Thus, the use of devazepide or other highly selective CCKAR antagonists would be a priority for asthma drug repurposing to limit the undesirable effects brought by the possibility of blocking the other CCK receptor (CCKBR)." (PMID 36599824, 2023).
breast carcinoma (1 paper, 2024). "NBDep identified CCKAR and WHSC as novel missense and amplification driver genes, respectively, in breast carcinoma." (PMID 38195844, 2024).
cholangiocarcinoma (1 paper, 2021). A carcinoma that arises from the intrahepatic biliary tree (intrahepatic cholangiocarcinoma) or from the junction, or adjacent to the junction, of the right and left hepatic ducts (hilar cholangiocarcinoma). "Previous studies have described the presence of KNG1 and CCKAR as biomarkers of various types of cancer, such as thyroid cancer, liver cancer, ovarian cancer, and cholangiocarcinoma." (PMID 34512870, 2021).
chronic pancreatitis (1 paper, 2022). A chronic inflammatory process causing damage and fibrosis of the pancreatic parenchyma. "In a therapeutic trial of chronic pancreatitis, oral administration of a CCKAR antagonist induced symptoms, such as abdominal fullness, diarrhea, and heartburn, in patients, although they were mild or moderate." (PMID 36262666, 2022).
Ewing sarcoma (1 paper, 2015). A small round cell tumor that lacks morphologic, immunohistochemical, and electron microscopic evidence of neuroectodermal differentiation. "Treatment of Ewing sarcoma cell lines with devazepide, a specific CCKAR antagonist derived from the benzodiazepine family, induced apoptosis in vitro and significantly reduced the tumor growth in a mouse xenograft model." (PMID 26258070, 2015).
gastric ulcer (1 paper, 2023). An ulcerated lesion in the mucosal surface of the stomach. "CCKAR antagonists are intended for gastric ulcer to inhibit gastrointestinal motility and gastric secretions and are known to possess favorable safety profile." (PMID 36599824, 2023).
keloid (1 paper, 2025). An irregularly shaped, elevated mark on the skin caused by deposits of excessive amounts of collagen during wound healing. "Furthermore, the neuroactive ligand-receptor interaction pathway exhibited substantial changes, with 31 genes, including GRIN2D, HTR7, and CCKAR were upregulated and 44 genes downregulated in keloid tissues compared to normal skin controls." (PMID 41562114, 2025). "Additionally, 14 genes such as GRIN2D, HTR7, and CCKAR were found to be upregulated in the calcium signaling pathway, while 43 genes, including ATP2A1, ADCY8, and MCOLN3, were significantly downregulated, suggesting that calcium signaling plays a critical role in the pathology of keloids." (PMID 41562114, 2025).
prostate carcinoma (1 paper, 2021). A carcinoma that arises from epithelial cells of the prostate gland. "Our study first described the upregulation of KNG1 and CCKAR in prostate cancer." (PMID 34512870, 2021).
sarcoma (1 paper, 2024). A usually aggressive malignant neoplasm of the soft tissue or bone. "In these sarcoma cell lines, CCKAR regulates collagen expression, which can be markedly decreased by IFNγ elevation." (PMID 39574893, 2024). "We focused on collagen because CCKAR, the most upregulated gene in sarcoma models that were resistant to attIL12-T cell treatment, is associated with collagen production, which may form immune-blocking walls to facilitate tumor development." (PMID 39574893, 2024).
skin tumors (1 paper, 2022). "Our study provides two important insights regarding the functions of CCKAR in skin tumors." (PMID 36262666, 2022).
tumor (9 papers, 2014 to 2024). "In this study, we discovered that CCKAR directly boosts collagen production by tumor cells in vitro and in vivo." (PMID 39574893, 2024). "Altogether, these results emphasized the importance of the transition from a TGFβ- to an IFNγ-dominated tumor microenvironment, which shuts down multiple pathways through which TGFβ and CCKAR signaling limit collagen expression." (PMID 39574893, 2024). "The robust induction of IFNγ suppressed both TGFβ-dependent SMAD3 activation and CCKAR-AKT signaling–mediated collagen expression in the tumor microenvironment." (PMID 39574893, 2024). "Compared with CCKBR, the function of CCKAR in tumorigenesis and tumor progression is much less studied." (PMID 36733361, 2022). "Further, stratification of band intensity in relation to the stage of tumor revealed significant increase (13.23%, P < 0.0001) in expression of CCKAR mRNA in stage III as compared with stage II GBC." (PMID 25025063, 2014). "Higher expression (26.94%, P < 0.0001) of CCKAR mRNA was observed in stage III as compared with stage II tumor." (PMID 25025063, 2014). "Mechanistically, the interaction between attIL12-TILs and autologous tumor cells synergized IFNγ production, which in combination with CCKAR downregulation reduced collagen expression through suppression of both TGFβ-stimulated SMAD activation and CCKAR-AKT signaling." (PMID 39574893, 2024). "CCKAR was highly expressed in NSCLC tissues compared with para-tumor tissues." (PMID 36733361, 2022). "In 12 pairs of NSCLC tissues and para-tumor tissues, CCKAR expression was detected with qRT-PCR." (PMID 36733361, 2022). "As the result, CCKAR in NSCLC was significantly higher than that in para-tumor tissues, suggesting that CCKAR may play an important role in NSCLC progression." (PMID 36733361, 2022). "Differential expression of CCKAR mRNA was also observed for tumor stage and differentiation." (PMID 25025063, 2014). "CCKAR expression in NSCLC and resected BM was assessed by IHC, and CCKAR mRNAs in NSCLC and para-tumor tissues were estimated by qRT-PCR." (PMID 36733361, 2022). "The expressions of CCKAR in NSCLC and corresponding tumor-adjacent tissues were detected with IHC and qRT-PCR." (PMID 36733361, 2022). "Unlike TGFβ, CCKAR’s role in tumor collagen expression is not well understood, but our RNA sequencing results found that CCKAR is highly overexpressed in ECM-rich resistant PDX models." (PMID 39574893, 2024). "The Smith group showed that treatment with a competitive CCK receptor (CCKAR) antagonist suppressed tumor initiation in non-obese KC mice and that HFD feeding could promote tumor growth in a CCKAR-dependent manner in an orthotopic transplant model." (PMID 37648285, 2023). "This disruption of collagen production by tumor cells required a simultaneous interaction between the CSV on autologous tumor cells, which is targeted by attIL12, and HLA-TCR on attIL12-TILs; when either interaction was abrogated, collagen production and CCKAR expression were not shut down." (PMID 39574893, 2024).
cancer (8 papers, 2015 to 2025). A tumor composed of atypical neoplastic, often pleomorphic cells that invade other tissues. "Beyond the impact of CCK on gallbladder function and the observed overexpression of CCKAR in specific cancers, our cellular model may also inform targeted anticancer therapies." (PMID 38013211, 2024). "We wish that more evidence on the important clinical significance of CCKAR could provide more fundamental research of how CCKAR is related with poor prognosis of cancer." (PMID 36733361, 2022). "In cancer study, the oncogenic role and mechanism of CCKAR are occasionally reported." (PMID 36733361, 2022).
metabolic disease (1 paper, 2022). A congenital disorder (due to inherited enzyme abnormality) or acquired (due to failure of a metabolically important organ) disorder resulting from an abnormal metabolic process. "CCKAR is a promising drug target for gastrointestinal and metabolic diseases." (PMID 36733361, 2022).
CCKAR also shares sentences with these, for which no sentence is quoted: gallbladder cancer (4 papers); diabetes (3); Arrhythmia (2); endotoxemia (2); metabolic syndrome (2); non-small cell lung carcinoma (2); pancreatitis (2); acute cholecystitis (1); acute pancreatitis (1); adenocarcinoma (1); airway hyperresponsiveness (1); Anorexia (1); Ataxia (1); bipolar disorder (1); blue nevus (1); celiac disease (1); cerebral edema (1); cholelithiasis (1); colorectal tumor (1); dependence (1); depression (1); diabetic neuropathy (1); esophageal cancer (1); esophageal tumor (1); functional dyspepsia (1); gastric cancer (1); gastric tumor (1); gastrointestinal disorders (1); hepatocellular carcinoma (1); Hyperglycemia (1).
A further 28 diseases each share a sentence with CCKAR in 1 paper.